SORL1 (sortilin related receptor 1)
Diseases named in the same sentence as SORL1 in open-access papers (continued):
Sharing a sentence is not in itself a finding about the gene and the disease.
Alzheimer disease (continued). "Collectively, and together with other recent observations, these findings suggest that one role for SORL1 is to contribute to endosomal degradation and recycling pathways in neurons, a conclusion that has both pathogenic and therapeutic implications for Alzheimer’s disease." (PMID 35226190, 2022). "The SORL1 gene encodes the protein SORLA and is associated with Alzheimer’s disease (AD)." (PMID 33726851, 2021). "One example is the protein SORL1, which is genetically linked to Alzheimer's disease." (PMID 32954517, 2020). "Interestingly, sortilin-related receptor 1 (SORL1), which likely plays a role in endocytosis and sorting and it has association to Alzheimer’s disease, was upregulated in liprin-α1 knockdown cells." (PMID 30005669, 2018). "SORL1 gene is a neuronal sorting receptor and is genetically associated with Alzheimer's disease." (PMID 22482075, 2012). "SORL1, the gene encoding the SORLA protein, has arisen as a potential therapeutic target for Alzheimer's disease (AD)." (PMID 41646738, 2026). "For example, in Alzheimer's disease (AD), numerous rare variants have been identified that are significantly associated with disease risk, including TREM2, ABCA7, and SORL1." (PMID 41482638, 2026). "Mutations in SORL1, encoding the sorting receptor Sortilin‐related receptor with A‐type repeats (SORLA), are found in individuals with Alzheimer's disease (AD)." (PMID 40928027, 2025). "The siRNA-NP targeting diverse molecular mechanisms implicated in Alzheimer's disease, to downregulate genes such as bridging integrator 1 (BIN1), sortilin-related receptor 1 (SORL1), and clusterin (CLU) has proven useful in various animal models." (PMID 41356731, 2025). "We studied the brain metabolic effects in genetically altered mice and minipigs with compromised expression of the Alzheimer’s disease gene SORL1 using 23Na-MRI and hyperpolarized [1-13C]pyruvate MRI." (PMID 38650831, 2024). "A study on late-onset Alzheimer’s disease focusing on protein–protein network interactions revealed eight genes with strong associations: APOE, SORL1, APOC1, CD33, CLU, TOMM40, CNTNAP2, and CACNA1C." (PMID 39228919, 2024). "We used loss of SORLA in an NPC-based drug screening model because of strong genetic and functional evidence supporting SORL1/SORLA’s involvement in Alzheimer’s disease." (PMID 38576795, 2024). "The sortilin-related receptor 1 (SORL1) gene, encoding the cellular endosomal sorting-related receptor with A-type repeats (SORLA), is now established as a causal gene for Alzheimer’s disease." (PMID 38650831, 2024). "To test feasibility of this approach for Alzheimer’s disease, we developed a cell morphology-based drug screen centred on the risk gene, SORL1 (which encodes the protein SORLA)." (PMID 38576795, 2024). "Though research on SORL1 has focused on its role in Alzheimer's disease via reducing the production of beta‐amyloid, the overexpression of it in adipose tissue has also been shown to enhance fat deposition." (PMID 37697678, 2023). "Differences in gene-wide DNA methylation of the Alzheimer’s disease (AD)-associated genes BIN1, HLA-DRB5, SORL1, SLC24A4, and ABCA7 are reported to be associated with AD in post-mortem brain samples." (PMID 36573011, 2023). "They observed a significant reduction in SORL1 expression in brain tissue of Alzheimer’s disease patients, postulating a protective effect of SORL1." (PMID 36092303, 2022). "APOE and CD33 expressions were especially high (and SORL1 expression and FDG PET SUVR were especially low) in regions most susceptible to Alzheimer’s disease, such as para-hippocampus and entorhinal cortex." (PMID 36092303, 2022). "A study using the Alzheimer’s Disease Neuroimaging Initiative database investigated the effect of eight SORL1 SNPs, including rs2298813 and rs1784933, on AD-related brain atrophy in subjects with normal cognition or mild cognitive impairment (MCI)." (PMID 35992588, 2022).
Alzheimer disease (continued). "The list included several known disease genes, such as INPP5D (Alzheimer’s disease), RAB27B (major depressive disorder, MDD), SORL1 (Alzheimer’s disease) and ZNF184 (MDD and schizophrenia)." (PMID 34446921, 2021). "In fact, variants at numerous other genetic loci related to endocytic trafficking and synaptic maintenance have been discovered as risk factors for Alzheimer’s disease (BIN1, PICALM, CD2AP, SORL1) and Parkinson’s disease (SNCA, LRRK2, SH3GL2/EndoA, RAB7L1)." (PMID 32286230, 2020). "Observations in post-mortem cerebral cortices of Alzheimer disease (AD) compared to healthy individuals showed that SORL1 levels increase and inversely correlate with SORL1-AS." (PMID 32435641, 2020). "Another participant in Alzheimer’s disease pathogenesis is SORL1 (Sortilin-related receptor 1) protein." (PMID 30871545, 2019). "SORL1 level is decreased in brain samples of patients with Alzheimer’s disease and knockout of SorLA leads to amyloid plaque accumulation in mice brains." (PMID 30871545, 2019). "Subsequently, the large IGAP (International Genomics of Alzheimer’s disease Project) study identified further genes encoding the endocytic proteins BIN1 (bridging integrator 1) and SORL1 (sortilin-related receptor) that reached genome-wide significance." (PMID 27430330, 2016). "Sortilin receptor 1 (SORL1) is involved in cellular trafficking of amyloid precursor protein and plays an essential role in amyloid-beta peptide generation in Alzheimer disease (AD)." (PMID 26996954, 2016). "Variations in sortilin-related receptor (SORL1) expression and function have been implicated in Alzheimers Disease (AD)." (PMID 19889229, 2009). "A more recent example, and one relevant to neurodegenerative diseases and the endo-lysosomal network, is provided by mutations in the Sortilin-Related Receptor 1 (SORL1), which has recently emerged as only the fourth gene that causes a rare, early-onset form of Alzheimer's disease." (PMID 38368937, 2024). "Furthermore, the sortilin-related receptor 1 (SORL1, SORLA) gene was shown to be strongly associated with Alzheimer’s disease." (PMID 39518906, 2024). "Increased Alzheimer’s disease risk has been repeatedly linked to variants in SORL1, particularly those conferring loss or decreased expression of SORLA, and lower SORL1 levels are observed in post-mortem brain samples from individuals with Alzheimer’s disease." (PMID 38576795, 2024). "Notably, both Apoe and Sorl1 are genes associated with Alzheimer’s disease risk, and play roles in regulating the clearance of amyloid protein β57; the interacting cell types detected by SpatialScope may help to elucidate the underlying genetic etiology behind Alzheimer’s disease." (PMID 38030617, 2023). "Apart from the “Total 17 NAbs” cluster, the NAb clusters for “Alzheimer’s disease” (SORL1, ADAM10, CLU and TREM2) and “Neurodegenerative disease” (SORL1, ADAM10, CLU and TREM2 and WWOX) showed the best diagnostic performance for AD with sensitivity (against 95% specificity) up to 0.759." (PMID 36922858, 2023). "In addition, SORL1, a gene associated with amyloidogenic processing of amyloid-beta precursor protein (APP) and Alzheimer's disease risk, was upregulated in aged β-cells, along with its ligand highly expressed in all four kinds of aged islet cells." (PMID 34691567, 2021). "SORL1 is strongly associated with both sporadic and familial forms of Alzheimer’s disease (AD), but a lack of information about alternatively spliced transcripts currently limits our understanding of the role of SORL1 in AD." (PMID 33726851, 2021). "Similarly, a reduced SORL1 expression has been found in Alzheimer’s disease (AD) patients." (PMID 35456392, 2022). "Thus, Sorl1 is considered the key factor in the pathogenesis of Alzheimer’s disease (AD)." (PMID 28915561, 2017).
Alzheimer disease (continued). "Dysregulated protein secretion and shedding are linked to neurologic and psychiatric diseases, including neurodegeneration, e.g., APP, APOE, SORL1, and TREM2 in Alzheimer's disease (AD), or the prion protein (PRNP) in prion disease." (PMID 32954517, 2020). "The sortilin-related receptor 1 (SORL1) gene, regulating the trafficking and recycling of amyloid precursor protein, has been related to Alzheimer’s disease (AD) and mild cognitive impairment (MCI)." (PMID 28034305, 2016). "The sorting protein-related receptor 1 (SORL1 or LR11) gene has been verified to play an important role in the pathologic process of β-amyloid (Aβ) formation and trafficking in Alzheimer's Disease (AD) by plenty of cytological and molecular biological studies." (PMID 27177090, 2016). "We additionally reviewed other risk genes associated with Alzheimer’s disease (ABCA7, SORL1 and TREM2), and no relevant variants were identified." (PMID 38287166, 2024). "Another study reported nine somatic mutations in the amyloid beta precursor protein (APP), sortilin-related receptor 1 (SORL1), nicastrin (NCSTN) and microtubule affinity-regulating kinase 4 (MARK4) genes in patients with Alzheimer’s disease by next-generation sequencing (NGS)." (PMID 37834279, 2023).
dementia (22 papers, 2009 to 2025). Loss of intellectual abilities interfering with an individual's social and occupational functions. "Two of the three most frequently identified genes in recent exome-wide association studies in unrelated individuals (TREM2 and SORL1) were significantly associated with proxy AD/dementia in this study and the third gene (ABCA7) was nominally significant." (PMID 36750708, 2023). "SORL1 was significantly associated with proxy AD/dementia when restricting to pLOF and high confidence missense variants (P = 1.75 × 10−9, Nvariants = 279)." (PMID 36750708, 2023). "It is noteworthy that the SORL1 variant, c.4384T > G (p.F1462V), has been identified in a sporadic case with AD who became forgetful at the age of 47 years and progressed to dementia at 51 years of age." (PMID 37051054, 2023). "In order to highlight variants of interest within TREM2 and SORL1, we investigated all variants in these genes which were moderately associated (P < 1 × 10−4) with proxy AD/dementia in the discovery and replication analyses." (PMID 36750708, 2023). "We report here that human cortical neurons derived from an individual with dementia as a result of a heterozygous SORL1 truncation mutation have half of control levels of SORL1 protein and disrupted endosomal trafficking, as do SORL1 heterozygous null neurons." (PMID 34133918, 2021). "Among the dementia genes we detected a loss of function mutation in the VPS10 of SORL1 (Aa 124–757), p.R744X, in 2/3 affected members of Family H displaying late-onset AD with severe language impairment and PPA with pyramidal signs." (PMID 33737586, 2021). "The association between cholesterol levels and AD risk, coupled with the functions of APOE and other genetic risk factors (e.g., SORL1), supports the role of lipid metabolism and transport in dementia." (PMID 30167451, 2018). "These may include factors already associated with cognitive dysfunction and dementia in other populations, such as apolipoprotein E, complement receptor 1, clusterin, sortilin-related receptor 1, catechol-O-methyltransferase and BDNF." (PMID 40235626, 2025). "The analysis revealed that SORL1 is associated with AD, Parkinson’s disease, and dementia." (PMID 38790243, 2024). "Furthermore, a third SORL1 variant, c.5195G > C, recently identified in a Swedish case control cohort included in the European Early-Onset Dementia (EU EOD) consortium study, was detected in two affected siblings in a third family with familial EOAD." (PMID 28595629, 2017). "Moreover, SORL1 expression was decreased as a function of AD-associated neuropathology prior to dementia, suggesting that the SORL1 reduction precedes conversion to AD." (PMID 19889229, 2009). "SORL1 and HEXA were significantly associated with proxy AD/dementia when testing all pLOF and high confidence missense variants (pLOF + REVEL > 50)." (PMID 36750708, 2023). "Previous studies have shown that the effect of the APOE gene on the risk of cognitive decline and dementia was modified by other genetic factors, including ABCA7, SORL1, PICALM, CR1, BIN1, and TREM2, showing complex gene-gene interactions." (PMID 34214049, 2021). "DNA from 183 AD cases and 303 healthy controls, were screened for variations in the SORL1 gene and constituted the case-control cohort from Sweden in a recent European Early-Onset Dementia (EU EOD) consortium study." (PMID 28595629, 2017). "Next, we screened II-1, II-2, II-4, and II-5 by whole exome sequencing, which revealed that all four subjects carry the SORL1 R953C variant and no other pathogenic variants known to be associated with dementia were identified." (PMID 38244079, 2024). "In addition, we also detected another three VUS in several autosomal dominant genes which can lead to other types of dementia or are recognized as risk factors for AD, such as GRN and SORL1." (PMID 37051054, 2023).
dementia (continued). "Moreover, thanks to NGS approach, we disclosed other variants in dementia-related genes, in particular FUS, ABCA7, CSF1R, DCTN1, SERPINI1 and SORL1." (PMID 33006056, 2021). "These cases suggest that SORL1 mutations might result in aggregation of a-synuclein through altered function of GDNF and further lead to appearance of core dementia with Lewy bodies features." (PMID 33879716, 2021). "Hence, the decreased SORL1 expression that we observed here in cognitively intact individuals with moderate AD neuropathology is suggestive that declines in SORL1 expression presage the onset of AD dementia." (PMID 19889229, 2009). "Targeted re-sequencing of the six candidate genes (LTF, MME, UBE4A SORL1, FAM221A and KDM2B) was performed in 35 EOAD cases with a family history of dementia." (PMID 28595629, 2017). "In terms of enrichment in the Jessen disease database, acrodysostosis (padjusted = 0.068) and dementia (padjusted = 0.068) were the most relevant diseases, involving PDE4D, Sortilin Related Receptor 1 (SORL1) and Parkin RBR E3 Ubiquitin Protein Ligase (PARK2) genes." (PMID 41473159, 2025). "APP, APOC1, APOE, SORL1, and MAPT are highly relevant common genes for AD and dementia." (PMID 38790243, 2024). "Further SORL1 gene-sequencing in 35 independent EOAD index cases as well as 183 EOAD cases, part of the reported European Early-Onset Dementia Consortium study, identified two additional SORL1-variants, c.3050-2A > G and c.5195G > C respectively, which segregated with disease." (PMID 28595629, 2017).
breast carcinoma (10 papers, 2018 to 2025). "Some non-canonical BMP4 target genes identified in this study, such as EPHA3 and SORL1, have been implicated in the progression of breast cancer." (PMID 38689334, 2024). "Due to the critical role of HER2 in breast cancer tumor progression and response to treatment, the inhibition or depletion of SORL1 is a potential therapeutic strategy for increasing the drug sensitivity of breast cancer cells." (PMID 39858026, 2025). "Our results and previous studies using this antibody in breast cancer models have demonstrated the feasibility of targeting SORL1 to overcome drug resistance in ovarian and breast cancers." (PMID 39858026, 2025). "The increased expression of SORL1 promotes HER2 recycling to the cell surface of breast cancer cells." (PMID 39858026, 2025). "It was shown that the extracellular domain of SORL1 interacts directly with HER2 and HER3, and an antibody targeting the extracellular domain of SORL1 can disrupt its ability to support HER2/HER3 trafficking in breast cancer cells." (PMID 39858026, 2025). "We focused on HER3 since HER2-HER3 dimers control SorLA/SORL1 expression and drive therapy resistance in breast cancer." (PMID 33420373, 2021). "This group further investigated the role of SORL1 in mediating targeted therapy resistance in breast cancer and discovered that SORL1 is necessary for HER2-HER3-driven oncogenic cell growth." (PMID 34976002, 2021). "Taken together, these results demonstrate that activation of HER2-HER3 positively regulates SorLA/SORL1 expression in breast cancer." (PMID 33420373, 2021). "It was first demonstrated in breast cancer models that SORL1 could bind to human epidermal growth factor receptor 2 (HER2) in the plasma membrane and intracellular vesicles, which regulates the endosomal trafficking and subcellular distribution of HER2." (PMID 39858026, 2025). "The deletion of SORL1 may affect the regulatory protein-induced cell proliferation enabling metastatic resistance to HER2 treatment in breast cancer cells." (PMID 35464477, 2022). "Taken together these data uncover a previously unknown mechanism by which HER2-HER3 signaling to ERK1/2 regulates SORL1 transcription leading to increased SorLA protein levels in breast cancer." (PMID 33420373, 2021). "Next, we used our previously established model of breast cancer cells expressing a specific and validated SORL1 shRNA to investigate the role of SorLA in clonogenic growth." (PMID 34564954, 2022). "In breast cancer cells, GSEA data analysis revealed liprin-α1 in the regulation of membrane microdomains (including TGFRB2), regulation of proteolysis (including SORL1, FN1) and peptidase activity and regulation of morphogenesis of epithelium." (PMID 30005669, 2018). "In addition, SORL1 expression was higher in tumors exhibiting high ERBB3 and ERBB2 expression (breast cancer patient data from the METABRIC study on the cBioportal database)." (PMID 33420373, 2021). "Interestingly, SORL1 also showed differences in gene expression after liprin-α1 knockdown in breast cancer and in HNSCC cell lines (SORL1; MDA-MB-231, p = 1.7^-15, (log2) fold change = 1.8, and HNSCC, p = 0.0099, (log2) fold change = 1.1)." (PMID 30005669, 2018).
mild cognitive impairment (10 papers, 2009 to 2025). "SORL1 is decreased in individuals with mild cognitive impairment and in patients with AD, and SORL1 deficiency has been linked to the development of sporadic AD." (PMID 31822279, 2019). "It is worth mentioning that Sorl1 and Syn1 were revealed as potential early biomarkers of cognitive impairment, since their mRNA levels in PBMC remained significantly low with the intake of the HF diets throughout the dietary intervention." (PMID 29566703, 2018). "SORL1 was firstly discovered to be relate to AD in 2004 and the protein level of SORL1 is found decreased in mild cognitive impairment (MCI) and LOAD patients, particularly in the vulnerable areas of the cortex and hippocampus." (PMID 27177090, 2016). "The aim of the present study was to elucidate whether SORL1 polymorphisms confer a risk of LOAD and mild cognitive impairment (MCI) in the Han Chinese population in Taiwan, as well as deciphering its effects on different cognitive domains." (PMID 28034305, 2016).
Parkinson disease (7 papers, 2014 to 2024). A progressive degenerative disorder of the central nervous system characterized by loss of dopamine producing neurons in the substantia nigra and the presence of Lewy bodies in the substantia nigra and locus coeruleus. "In a case report, 4 AD patients with Parkinsonism and psychiatric symptoms were found to have novel mutations in SORL1, with two mutations at the VPS10P region, where rs2298813 is located." (PMID 35992588, 2022).